RNU1-65P (RNA, U1 small nuclear 65, pseudogene)
Gene: Small nuclear RNA gene on chromosome 10 (84,003,332 to 84,003,479, forward strand). Ensembl gene ENSG00000200789.
Homologues: Orthologues: macaque U1 (89% identical), chimpanzee U1 (87% identical), guinea pig U1 (63% identical). Paralogues in human: RNU1-1 (81% identical), RNU1-2 (81% identical), RNU1-27P (81% identical), RNU1-28P (81% identical), RNU1-3 (81% identical), RNU1-4 (81% identical), RNVU1-1 (81% identical), RNVU1-18 (81% identical), RNVU1-29 (81% identical), RNVU1-31 (81% identical), U1 (81% identical), RNVU1-28 (80% identical), and 133 more.